BRAF (B-Raf proto-oncogene, serine/threonine kinase)
Diseases named in the same sentence as BRAF in open-access papers (continued):
Sharing a sentence is not in itself a finding about the gene and the disease.
melanoma (continued). "Various authors claim that BRAF V600E heterogeneity present in melanoma, could be due to tumor sampling, the detection method used, or secondary to biological differences." (PMID 28039443, 2017). "For selected mutation in melanoma (NRAS Q61K and BRAF V600E), and for each of the PMS2 promoter mutations, the median, minimum, and maximum allele fraction (fraction of reads at that position showing the mutation) and number of specimens with that mutation are provided." (PMID 28420421, 2017). "Indeed, EDNRB depletion through RNAi prevented EDN1 from protecting melanoma cells from BRAF inhibition." (PMID 28606996, 2017). "Its specificity and sensitivity to identify the BRAF V600E gene mutation have been verified in many series of tumors, including melanoma and PTC, and it could be used as a surrogate of genetic detection of BRAF V600E mutation." (PMID 28974264, 2017). "The combination has become a new standard of treatment for BRAF-mutant advanced melanoma." (PMID 29137342, 2017). "In melanoma patients, the usage of BRAF inhibitors may lead to the development of secondary cutaneous squamous cell carcinoma." (PMID 28829399, 2017). "Indeed, patients with BRAF V600-mutant melanoma had values of sCD73 enzyme activity similar to those measured in BRAF wild-type melanoma (P = 0.99)." (PMID 29202855, 2017). "To investigate if AZD7545 could delay or influence the occurrence of BRAF inhibitor resistance we tested the combination of the two inhibitors on melanoma cell growth." (PMID 28595656, 2017). "Significantly improved PFS has been observed in BRAF-mutant melanomas when BRAF and MEK inhibitors are used in combination; median PFS of 9.9 months was reported from a study of vemurafenib+cobimetinib, and PFS of 9.3 months was reported from a study of dabrafenib+trametinib." (PMID 28103611, 2017). "MEK mutants have been proposed to drive resistance to BRAF inhibition in melanoma." (PMID 28263969, 2017). "BRAF-targeted kinase inhibitors have become increasingly important in melanoma treatment." (PMID 29176861, 2017). "We have established stable cell lines with NOXA knockdown using an shRNA-mediated approach, and found that knockdown of NOXA significantly protected against the combination-induced disruption of spheres (P<0.05) in both BRAF and NRAS mutated melanoma cell lines." (PMID 27086916, 2017). "Due to the central role played by the BRAF/MAPK pathway in melanoma proliferation and cell cycle progression we first assessed if glucose restriction could affect ERK activation." (PMID 28380427, 2017). "Interestingly, MET activation has been identified as a mechanism of resistance to BRAF inhibition in melanoma." (PMID 28103611, 2017). "Similar results have earlier been indicated for BRAF‐mutant melanoma." (PMID 28267273, 2017). "Blocking the BRAF‐MEK pathway–commonly hyperactive in melanoma–has proved worthwhile." (PMID 28463413, 2017). "Finally miR-200c was shown to be downregulated in melanomas that acquire resistance to BRAF inhibitors compared to pretreatment tumor biopsies, in which its target genes are conversely up-regulated." (PMID 28118616, 2017). "This may be due to the fact that different molecular backgrounds define sensitivity, such as is apparent clinically with the contrasting responses seen with single agent BRAF inhibitors in melanoma and colorectal cancers." (PMID 28829765, 2017). "Suppression of ERK activation by RAF inhibitor in a BRAF V600-mutated melanoma leads to relief of negative feedback upstream of RAF and re-activation of RAS." (PMID 29285228, 2017). "Additionally, ERBB3 up-regulation is also a mechanism of resistance to anti-BRAF therapies; and has been shown to promote melanoma metastasis." (PMID 28060735, 2017).
melanoma (continued). "For example, a subset of lung cancer patients which do not bear activating EGFR mutations can achieve clinical responses to EGFR inhibitors, or also a good proportion of BRAF mutated melanoma patients do not respond to BRAF inhibitors." (PMID 28903768, 2017). "For example, BRAF mutant melanomas are highly addicted to the MAPK pathway." (PMID 28431544, 2017). "However, in melanomas harbouring mutant BRAF, Zeb2 is dynamically switched on/off and inversely associated with MAPK activation." (PMID 29050198, 2017). "We therefore hypothesize that elevated DUSP6 levels in melanoma are one mechanism for compensating BRAF V600E hyperactivation, which might otherwise trigger apoptosis via ERK1/2 downstream targets." (PMID 28423600, 2017). "The cytotoxic effect of BRAF inhibition may be enhanced due to the presence of dysfunctional mitochondria in melanoma cells, resulting in increased ROS production." (PMID 29137417, 2017). "In this work, we show that HDACi treatment induces significantly the abundance of PMCA4b in melanoma cells, irrespective of their BRAF mutational status but in a cell-type-dependent manner." (PMID 28596940, 2017). "However, the clinical experience with BRAF inhibitors and in particular with Vemurafenib has also shown that the efficacy of long-term treatment for patients with melanoma is hampered by the development of acquired drug resistance." (PMID 29113311, 2017). "These pathways could act as alternative survival routes for melanoma cells when BRAF signaling has been inhibited." (PMID 29100459, 2017). "Indeed, resistance to BRAF/MEK inhibition has been observed in up to one-third of melanoma patients, with genetic analyses revealing most had acquired either activating mutations in additional MAPK pathway members or in compensatory signaling pathways." (PMID 29104272, 2017). "MET activation, which may be driven by stromal HGF expression, has been shown to mediate melanoma growth, dissemination, and resistance to BRAF inhibition in multiple preclinical models." (PMID 28103611, 2017). "Our data suggest that forcing tumor glycolysis in melanoma using zalcitabine or other similar approaches may be an adjunct to increase the efficacy of targeted BRAF therapy." (PMID 28205616, 2017). "Another common side effect of BRAF inhibitors is the development of new BRAFwt and RASmt melanoma, which may be explained by a paradoxical activation of the MAPK pathway in BRAFwt melanoma." (PMID 28350340, 2017). "Moreover, the HDACis also enhanced the expression of the housekeeping PMCA1 isoform in the BRAF-mutant cells, suggesting an even more complex role of the PMCAs in the Ca2+ homeostasis of melanoma cells." (PMID 28596940, 2017). "Similarly designed experiments demonstrated that oncogenic PD-L1 expression in BRAF.PTEN melanoma tumors only slightly inhibited antitumor immunity, whereas immunogenic PD-L1 expression on non-tumor cells was critical for immune evasion." (PMID 29255458, 2017). "However, the duration of response of metastatic melanomas to single-agent BRAF inhibition is limited, largely due to MAPK-pathway reactivation, achieved through multiple means." (PMID 28982154, 2017). "However, in a feasibility trial with a limited number of patients with advanced malignancies, a BRAF-positive melanoma patient seemed to benefit most from consumption of ketogenic diet after BRAF-inhibitor resistance." (PMID 29029389, 2017). "The BRAF V600E mutation was present in 19% of nevi and 26% of melanomas, but not in primary acquired melanosis (PAM)." (PMID 28938534, 2017). "One mutated case was a superficial spreading melanoma diagnosed in 1999, that did not display BRAF, NRAS and TERT promoter mutations, and the patient was alive at the last follow-up (180 months)." (PMID 28662141, 2017). "BRAF-mutant melanoma patients showed a tendency for better overall and relative survival." (PMID 28797232, 2017).
melanoma (continued). "Notably, the response in a patient with BRAF L597R mutant melanoma is consistent with observations with other MEK1/2 inhibitors, including trametinib, which have shown activity in BRAF-mutant melanoma." (PMID 27650277, 2017). "Among 77 patients, 39 (51%) had BRAF‐mutant and 33 (43%) had BRAF wild‐type melanoma." (PMID 28719152, 2017). "In particular, we demonstrate that the treatment of BRAF mutant melanoma cells with BRAF kinase inhibitors (PLX4032 or GSK2118436) increases the phosphorylation of the PDH-E1α subunit, while this is not the case in cells harboring BRAFWT/NRASmut, a process which is facilitated by PDKs." (PMID 28595656, 2017). "BRAFV600E melanoma treated with BRAF inhibitors may acquire drug resistance through flexible switching between different RAF isoforms capable of reactivating the ERK pathway." (PMID 29100459, 2017). "BRAF inhibition augments melanoma antigen expression and maintains T cell function." (PMID 28659921, 2017). "The observation that RhoJ is not mutated in melanoma but yet plays a more important role in the growth of BRAF mutant cells ranging from nevi to tumors indicate that RhoJ is part of a normal signaling pathway that is co-opted to speed tumor development." (PMID 28753606, 2017). "Since BRAF(V600E) activation requires a T>A transversion at nucleotide 1799, BRAF non-CSD mutations do not resemble nucleotide transitions typically found in sun-induced melanoma damage arising from cyclobutane pyrimidine dimers (CPDs)." (PMID 28265786, 2017). "However, ERK cascade inhibitors have been proven beneficial almost exclusively for BRAF mutant melanomas." (PMID 29180761, 2017). "In addition to observational studies describing the methylome of melanoma, several studies suggest a BRAF-driven mechanism of aberrant methylation of specific genomic loci in melanoma." (PMID 28396701, 2017). "This strategy has already proven successful with the addition of the MEK inhibitor trametinib to the BRAF inhibitor dabrafenib, improving both response rates and progression-free survival compared with dabrafenib alone in patients with BRAF V600 mutant melanoma." (PMID 28424891, 2017). "Future development of WEE1 ‛epigenetic inhibitor’ could facilitate specific targeting of many of WT BRAF melanomas, GBMs, triple negative breast cancers (TNBCs) and castration resistant prostate (CRPCs), which currently have a few therapeutic options." (PMID 29290954, 2017). "We considered this finding of worth to be followed-up since previous experimental studies, which did not specifically focus on the subgroup of MSI CRCs, had suggested that vemurafenib is apparently much less efficient in BRAF mutant CRC than in malignant melanoma." (PMID 29050239, 2017). "Moreover, PINK1 is known to be induced by the PTEN pathway, which has previously been shown to be involved in melanoma progression and BRAF inhibitor resistance." (PMID 28173755, 2017). "Furthermore, uPAR inhibitors have been described to be efficacious also in melanoma cells with acquired resistance to BRAF and MEK inhibitors." (PMID 29216889, 2017). "Finally, therapies that associate BRAF inhibitors with MEK inhibitors (dabrafenib with trametinib and vemurafenib with cobimetinib) are the current treatment strategies for BRAF-mutant advanced cancers, including melanoma." (PMID 29064427, 2017). "Interestingly, the data shown that combination of ABT-737 and 4-HPR significantly eliminate ALDH+ CSCs in multiple melanoma cell lines including BRAF and NRAS mutant cells." (PMID 28137308, 2017). "The results of a systematic proof-of-concept cell viability screen led to subsequent hypothesis-based experiments, which identified DUSP6 as context-specific synthetic lethal target in melanomas with BRAF V600E mediated ERK1/2 activation." (PMID 28423600, 2017). "Furthermore, the combination of BRAF and HDACis increased cell death and even overcame resistance in BRAF-mutant melanoma cells." (PMID 28596940, 2017).
melanoma (continued). "Similarly, melanoma cells selected for resistance to the BRAF inhibitor vemurafenib expressed higher levels of CD47." (PMID 29050218, 2017). "Consistent with our hypothesis that JNK conveys intrinsic or acquired resistance to lapatinib, JNK-IN-8 was recently used to overcome resistance to a BRAF inhibitor in melanoma cells." (PMID 29285221, 2017). "Other BRAF mutations (non-V600 mutations) are rare in melanoma and targeted therapy is not indicated for patients with these mutations due to reduced response rates." (PMID 29181212, 2017). "The compound was awarded the status of orphan drug by the FDA in 2014 for malignant melanoma with the BRAFV600 mutation, and was then approved for combination treatment with vemurafenib for unresectable or metastatic melanoma with a BRAF V600E or V600K mutation in November 2015." (PMID 28954413, 2017). "Even though the genotype was not a risk factor in multivariate analysis, BRAF-mutant melanoma patients showed a trend towards better overall and relative survival." (PMID 28797232, 2017). "In conclusion, targeted therapies including BRAF inhibitors and immune checkpoint inhibitors have become an important backbone in the treatment of melanoma BM and the on-going clinical trials will further redefine the clinical practice in this particular patient cohort." (PMID 28374234, 2017). "Altogether, we estimate from both series that 36.2% of melanomas with BRAF/NRAS mutations have a non-heterozygous oncogenic allele." (PMID 28668077, 2017). "On the other hand, non-CSD melanomas show a predominance of BRAF(V600E) mutations arising from nevi." (PMID 28265786, 2017). "Likewise, an activation of v-raf murine sarcoma viral oncogene homolog B (BRAF/V600E) has a capacity to induce senescence in both human and mouse melanoma models." (PMID 29312442, 2017). "Thus, in the context of mutant BRAF inhibition in melanoma, the activation of Zeb2/MerTK signaling plays an important role in mediating cancer cell survival and resistance." (PMID 29050198, 2017). "Although BRAF-activated melanomas initially have been the most successful melanoma subset due to targeted therapies, they will ultimately develop resistance and there is rapid progress in complementary approaches especially ones taking advantage of the immune system to fight cancer cells." (PMID 28265786, 2017). "The V600 BRAF mutation is the most common in melanoma, and mutation‐specific inhibitors are effectively used to treat melanoma and some of the nonmelanoma cancers with the same mutation." (PMID 28182330, 2017). "While both methods have been successfully employed in identifying chemical inhibitor resistant mutations, such as identifying the imatinib-resistant BCR-ABL in chronic myeloid leukemia or the vemurafenib-resistant BRAF mutants in melanoma, some limitations still persist." (PMID 28231254, 2017). "Clinical trials using the WNT pathway inhibitor LGK974 [NCT01351103] alone and in conjunction with anti PD-1 immune checkpoint inhibition in patients with melanoma, B-Raf serine/threonine kinase (BRAF) mutant colorectal cancer and triple negative breast cancer are currently recruiting." (PMID 28714919, 2017). "Nagore and colleagues have shown that melanoma patients harboring these specific TERT promoter mutations, in combination with BRAF/NRAS mutations within their tumor tissue, have a significantly shorter disease free survival than patients without this combination." (PMID 29108273, 2017). "Developing new PLGG models replicating such druggable mutation would be highly desired not only to understand the functional role of BRAF V600E mutation in driving PLGG recurrence, but also for future examination of drug resistance as has been noted in melanomas." (PMID 29152094, 2017).
melanoma (continued). "To examine the potential clinical relevance of CD47 upregulation in acquired resistance to BRAF inhibitors in vivo, we took advantage of primary melanoma cell cultures of paired BRAFV600E melanoma biopsy samples from five patients pre- and post-treatment with vemurafenib." (PMID 29050218, 2017). "Therefore, we propose that simultaneous targeting of BRAFV600E and autophagy/MerTK signaling axes is a rational strategy for overcoming resistance to BRAF inhibitors in melanoma." (PMID 29050198, 2017). "For example, acquired BRAF inhibitor resistance in melanoma that results from the downstream activation of MEK (MAPK/ERK Kinase) effector proteins has been mitigated through combinatorial approaches targeting both BRAF and MEK." (PMID 29104272, 2017). "Another study in BRAF V600E mouse melanoma transplants and in de novo melanomas demonstrated that BRAF inhibitor downregulated tumor expression of chemokine (C-C motif) ligand 2 (CCL2), and resulted in a robust increase in CD8+ T/FoxP3+CD4+ T cell ratio and natural killer (NK) cells." (PMID 29156850, 2017). "Finally, other less frequently mutated melanoma genes (KRAS, HRAS, KIT, GNAQ, GNA11) were enriched in tumors wild‐type for BRAF, NRAS, and NF1." (PMID 28267273, 2017). "The therapy of melanoma changed radically with the identification of recurrent mutations in genes coding for members of the MAPK pathway, which then led to the design of targeted inhibitors for both BRAF and MEK tyrosine kinases." (PMID 28199980, 2017). "To investigate changes in NGFR levels across a larger cohort of BRAF‐mutant melanoma patients, we analyzed two published RNA‐seq datasets involving matched samples from 21 tumors pre‐treatment and following emergence of resistance to different combinations of RAF/MEK inhibitors." (PMID 28069687, 2017). "Similar to the metabolic effects of BRAF inhibition, DCA switches glycolytic cancer cells away from glycolysis towards mitochondrial respiration, but unlike PLX4032, the effect of DCA is not limited to BRAF-mutated melanomas." (PMID 29137417, 2017). "Consequently, clinical mutation screening beyond BRAF and NRAS would be of significance in the clinical setting of melanoma." (PMID 28267273, 2017). "Interestingly, BRAF (V600E) mutation in melanoma cells does not evidently affect PD-L1 expression; however, PD-L1 expression is attenuated by treatment with BRAF inhibitor, but enhanced when melanoma cells become resistant to BRAF inhibitor." (PMID 28629173, 2017). "In this study, we identify a novel therapeutic vulnerability for BRAF mutant melanoma tumors." (PMID 28753606, 2017). "Activating mutations of BRAF, the majority occurring in BRAFV600, are frequently detected in melanoma; however, the prognostic significance remains unclear." (PMID 29176861, 2017). "In melanoma, metabolic rewiring for glycolysis may be driven by multiple signaling pathways, including BRAF-driven MAPK hyperactivation that negatively regulates OXPHOS and PI3K/AKT/mTOR/HIF1α signaling that positively regulates glycolysis." (PMID 29209327, 2017). "Coexistence of BRAF V600E mutation and EZH2 gain is rather prevalent in melanoma." (PMID 29202777, 2017). "Furthermore, we used phenformin as a single agent, but, in the context of other reports, phenformin also shows synergistic effects with other anti-cancer drugs, like combinational therapy with vemurafenib, a BRAF inhibitor, in melanoma cells." (PMID 28947975, 2017). "Despite the high frequency of BRAF mutations in melanoma, we did not observe association of BRAF mutation with any immune signature there." (PMID 28749946, 2017). "In a global multi-center, randomized, open-label and controlled trial, 322 melanoma patients with the BRAF V600E or V600K-mutant were allocated with the ratio of 2:1 into either the trametinib group or conventional chemotherapy group (dacarbazine or paclitaxel), respectively." (PMID 28954413, 2017).